ACE (angiotensin I converting enzyme)
Diseases named in the same sentence as ACE in open-access papers (continued):
Sharing a sentence is not in itself a finding about the gene and the disease.
Hypertension (continued). "We have shown that ACE2 is genetically correlated with a series of vascular traits, whereas its causal role was detected only for CVD-related phenotypes; in contrast, the hypertension target ACE showed a clear causal effect on blood pressure." (PMID 35387486, 2022). "It plays a key role in diabetes, renal, and cardiovascular disease by counterbalancing the ACE/renin angiotensin aldosterone system which is associated with sodium and water retention, vasoconstriction, hypertension, and accelerated thrombosis." (PMID 35962323, 2022). "ACE inhibitors and angiotensin II receptor blockers (ARBs) are key drugs in the treatment of hypertension, particularly in patients with multiple cardiovascular risk factors, heart failure, diabetes mellitus, and kidney impairment." (PMID 35621847, 2022). "Ramipril is a widely used ACE compound because of its effectiveness in the treatment of hypertension and heart failure, as well as its low risk of adverse effects." (PMID 35976917, 2022). "The present study was the first one to be done in the Ethiopian population and revealed that the DD genotype of the ACE gene is strongly associated with the risk of hypertension." (PMID 36355860, 2022). "The present study found that the DD genotype and D allele of the ACE gene has had a strong association with a high risk of hypertension in the study population." (PMID 36355860, 2022). "The ACE gene DD genotype and D allele predisposes to the occurrence of hypertension in our study participants." (PMID 36355860, 2022). "Angiotensin converting enzyme (ACE) overproduction-induced hypertension is the main risk factor for common cardiovascular diseases, which are a significant cause of morbidity and mortality globally." (PMID 36547528, 2022). "On the other hand, the AGTR1 and CYP11B2 genes are linked to the ACE inhibitor pathway and are used to treat cardiovascular disorders such as hypertension." (PMID 35629146, 2022). "It has long been established that ACE genotypes are linked to hypertension and so cardiovascular disease and we show that hypertension is a leading risk factor for disease severity." (PMID 35996506, 2022). "Some studies of ACE gene in the Mexican population have reported the I/D polymorphism as a genetic marker of susceptibility for cardiovascular disease, diabetes, and hypertension diseases." (PMID 35250987, 2022). "Hypertension is a major risk factor leading to cardiovascular disease, and is frequently treated with angiotensin I-converting enzyme (ACE) inhibitory peptides." (PMID 35479750, 2022). "Studies have shown that meat proteins exert numerous effects, including pharmaceutical effects against cardiovascular disease (CVD) that is caused by high blood pressure via the inhibition of angiotensin-I converting enzyme (ACE)." (PMID 35159571, 2022). "Variant rs4291 of the ACE gene was strongly associated with the incidence of high blood pressure; however, its direct association with blood pressure response to amlodipine remains elusive." (PMID 36011305, 2022). "It is a specific competitive inhibitor of ACE, and the lowered production in angiotensin II causes a reduction in blood pressure and cardiovascular remodeling both in humans with essential hypertension and in different animal models of arterial hypertension." (PMID 36014793, 2022). "The distribution of DD genotypes and D allele of the ACE gene were 48.4% and 63% in essential hypertensive patients, respectively, while it were 29.7% and 42.2% in control subjects respectively." (PMID 36355860, 2022). "The association between ACE I/D (rs4340) and 2350A>G (rs4343) polymorphisms has been found in several studies, including ones that investigated high blood pressure, systemic lupus erythematous, diabetic nephropathy, Alzheimer’s disease, and renal diseases." (PMID 35741131, 2022). "The only comorbidity positively associated with a positive test was hypertension and the use of ACE inhibitors." (PMID 34125032, 2021).
Hypertension (continued). "The bioactive potential was also assessed through the ability of the extracts to inhibit digestive enzymes linked to diabetes (α-amylase, α- and β-glucosidases) and hypertension (angiotensin-converting enzyme, ACE)." (PMID 34299476, 2021). "Older patients, with associated hypertension and diabetes mellitus, those receiving ACE inhibitors and with lower preoperative hemoglobin and higher serum uric acid, had higher incidence of AKI." (PMID 33805325, 2021). "Analyzing further questionnaire items, the moderate to high risk group showed a significantly higher proportion of arterial hypertension, DM and medication with betablocker (p = 0.047) or ACE/AT1 inhibitors (p = 0.047), with higher ASA physical status." (PMID 34006226, 2021). "On both axes of the RAAS system, the consequence of the ACE/Ang II/AT1R axis causes hypertension and exacerbates lung injury, while it is counteracted by the ACE2/Ang 1–7/MasR axis, protecting the lung function." (PMID 33494713, 2021). "Angiotensin-converting enzyme (ACE) catalyzes specific reactions involved in blood pressure regulation, which makes this enzyme responsible for hypertension and a key target in the therapy of such a risk factor of cardiovascular disease." (PMID 33572713, 2021). "The primary association between patients with pre-existing hypertension and COVID-19 is related to the use of Angiotensin Converting Enzyme (ACE) inhibitors, a common anti-hypertensive medication." (PMID 33466289, 2021). "ACE inhibitors are well-established medications for hypertension, which is also a major risk of cognitive impairment and dementia and of death by COVID-19." (PMID 34947975, 2021). "ACE inhibitors can be used as treatment options for hypertension and other health conditions, while alterations of the ACE gene are associated with AD." (PMID 34947975, 2021). "Hypertension has been associated as one of the main causes of cardiovascular diseases, with the angiotensin-converting enzyme (ACE) being one of the major enzymes involved in the process of blood pressure regulation." (PMID 34500661, 2021). "Excessive ACE activity causes an increase in blood pressure and a decrease in the lumen of blood vessels, which in turn leads to the development of hypertension." (PMID 34959917, 2021). "The inhibition of renin and ACE in the RAS pathway is considered an important therapeutic strategy in treating hypertension which is a controllable risk factor for cardiovascular diseases." (PMID 34681387, 2021). "Supervisor and trainee discuss the risk of inducing hypotension when starting ACE inhibitors and diuretics at the same time to treat hypertension." (PMID 34176147, 2021). "Nominal parameters were the following: existence of preoperative chronic renal failure, preoperative clopidogrel therapy and preoperative arterial hypertension associated with calcium channel blockers or ACE inhibitor use." (PMID 33882969, 2021). "The presence of the chronic renal failure, recent clopidogrel use, and arterial hypertension associated with calcium channel blockers or ACE inhibitor use need to be assessed as well." (PMID 33882969, 2021). "As ACE inhibitors are frequently prescribed to treat hypertension, we posit that they can increase susceptibility to SARS-CoV-2." (PMID 34671355, 2021). "Chitin, chitosan, and their derivatives also act as inhibitors of ACE, an enzyme associated with hypertension." (PMID 34203174, 2021). "In these patients, Ang II which causes hypertension and inflammation is increased, and ACE/Ang II/AT1R is activated." (PMID 33953641, 2021). "The ACE DD polymorphism is also associated with hypertension, acute respiratory distress and diabetic nephropathy, all considered high risk for COVID-19 infection and outcomes." (PMID 32901433, 2021).
Hypertension (continued). "There were also warnings against independently discontinuing medication such as ACE inhibitors, which are used to treat high blood pressure and were for a while suspected of increasing the risk of a severe course of COVID-19." (PMID 35146280, 2021). "Single-nucleotide polymorphism (rs1799752) on the ACE gene was investigated for its implication on high blood pressure in different sub-Saharan Africa countries." (PMID 33917487, 2021). "GA also has demonstrated a positive effect on CVD risk, as evidence suggests it can act as an ACE inhibitor yielding results similar to the effects of captopril, a medication used to treat high blood pressure." (PMID 33494165, 2021). "A recent study reported a higher prevalence of ACE D/D genotype in severe COVID-19 patients as compared to those with mild-disease, even though this association was dependent on the presence of hypertension comorbidity." (PMID 33585520, 2020). "ACE D/D polymorphism has been associated not only with hypertension, though also with obesity and diabetes, chronic conditions highly suggestive of high risk for COVID-19 infection, as well as for poor outcomes of the disease." (PMID 33585520, 2020). "In turn, peptides with ACE inhibitor activity contribute to the reduction of blood pressure in patients with arterial hypertension, which is a risk factor for the development of cardiovascular diseases." (PMID 33066429, 2020). "Studies have shown that the renin–angiotensin system (RAS) is associated with worsening of hypertension and various types of organopathies via the angiotensin-converting enzyme (ACE)/angiotensin (Ang) II (Ang II)/Ang II type 1 receptor axis." (PMID 32458985, 2020). "In melatonin-deficient hypertension, the classical angiotensin-converting enzyme (ACE)–Ang II–angiotensin type 1 receptor (AT1R) axis is activated." (PMID 32210175, 2020). "ACE is associated with hypertension and remains an important target for the discovery of anti-hypertensive drugs due to these effects." (PMID 32210030, 2020). "The angiotensin converting enzyme (ACE) enzyme is an essential component of human metabolism, and its dysregulation is associated with a number of different clinical conditions, including hypertension." (PMID 32670694, 2020). "The European Society of Cardiology recommends not discontinuing either of the drugs as the potential risks associated with uncontrolled hypertension seem to outweigh the risks of ACE inhibition worsening the COVID 19 infection." (PMID 32670694, 2020). "Squash is also a rich source of phenolic antioxidants and has natural angiotensin-converting enzyme (ACE) inhibitors, which are important for T2D-linked hypertension management." (PMID 32258994, 2020). "Some authors have postulated an association between ACE inhibitors or angiotensin receptor blockers (ARBs) and the increased severity of the disease as an explanation for the association with hypertension and poorer prognosis." (PMID 33334400, 2020). "The bioactive peptides were also found to inhibit renin and angiotensin-converting enzyme (ACE), two components known to be associated with hypertension." (PMID 33363196, 2020). "The observed lower ACE activity in the lanosteryl triterpene treated groups further suggests the potential role of RA-3 in management of hypertension, another important risk factor of nephropathy." (PMID 32887389, 2020). "ACE inhibitors and angiotensin II type-I receptor blockers, which are commonly prescribed in the context of arterial hypertension, have also been suspected to increase the risk of developing severe and fatal COVID-19." (PMID 33362199, 2020). "In humans, aberrant methylation of angiotensin II receptor type 1 promoter and angiotensin I converting enzyme was associated with hypertension." (PMID 32883357, 2020).
Hypertension (continued). "Ash gourd (76.51%), brinjal (72.48%), and snake gourd (66.82%) extracts were the most effective inhibitors of angiotensin-converting enzyme (ACE), an enzyme whose excessive activities have been associated with hypertension." (PMID 32610462, 2020). "The strong redundant interactions of red meat consumption, smoking, BMI, and hypercholesterolemia are additive to high blood pressure, ACE, and NOS3 genotype polymorphisms, all being able to contribute to cardiovascular risk." (PMID 32714484, 2020). "The increased salt content in the diet stimulates glomerular oxidative stress, which leads to the AT1 receptor, MR, and ACE up-regulation, subsequently causing hyperbole in sodium transporters, and providing to sodium retention and hypertension." (PMID 31726743, 2019). "Despite their common utilization in hypertension and heart failure, adverse events associated with ACE inhibitors remain a major challenge for the physicians." (PMID 31700727, 2019). "It was revealed that ACE plays a key role in hypertension, its dysfunction being the most frequent cause of hypertension." (PMID 30875817, 2019). "ACE inhibitors and ARBs reduce incidence of new-onset diabetes in large randomized trials in hypertension, chronic heart failure, and patients at high risk for cardiovascular events." (PMID 31262355, 2019). "In conclusion, the findings suggest a large scale multi-ethnic study is needed to further elucidate the effect(s) of ACE I/D polymorphism on hypertension." (PMID 30763326, 2019). "Polymorphisms in components of RAAS constitute the focus of the genetic association studies related to hypertension, been the insertion/deletion (I/D) polymorphism (rs4646994) of the ACE gene one of the most studied in this field." (PMID 31430320, 2019). "This study found that ACE I/D polymorphism is associated with hypertension in two models, specifically the allele contrast model, and the recessive, dominant and homozygous co- dominant model." (PMID 30763326, 2019). "In Indian adults, polymorphisms in the angiotensin-converting enzyme (ACE) gene, leading to elevated levels of angiotensin II (Ang II) and thus hypertension, have been associated with protection against cerebral malaria." (PMID 31810471, 2019). "In our study design, at least 3500 cases and 3500 controls are required to obtain an 80% power to detect if there is a true association between rs1799752 in ACE and hypertension." (PMID 31511791, 2019). "Canada Hypertension Guidelines 2018 recommend that in treatment of HT in association with LVH “Initial therapy can be drug treatment using ACE inhibitors, ARBs, long-acting CCBs, or thiazide/thiazide-like diuretics." (PMID 31807315, 2019). "It has been demonstrated that ACE makes a positive contribution to hypertension, which is the most common risk factor of heart diseases and threats to the life of one-fourth of adults in the world." (PMID 31842519, 2019). "In contrast to Caucasian populations, there are a limited number of studies in Asian populations on the relationship of the ACE polymorphisms and hypertension." (PMID 31511791, 2019). "The association between ACE I/D (rs4340) and 2350A>G (rs4343) polymorphisms has been found in several studies including high blood pressure, systemic lupus erythematous, CAD, diabetic nephropathy, Alzheimer’s disease and renal diseases 6,7." (PMID 30800252, 2019). "ACE I/D polymorphism is associated with essential hypertension in the allele contrast model, dominant allele contrast model, and homozygous codominance model in Africa." (PMID 30763326, 2019). "In this gene, ACE I/D polymorphism is associated with essential hypertension in studies conducted in Africa." (PMID 30763326, 2019). "On subgroup analysis by classifying studies into North Africa and SSA, the findings showed that ACE I/D polymorphism was associated with essential hypertension in patients from SSA." (PMID 30763326, 2019).
Hypertension (continued). "ACE I/D polymorphism is associated with essential hypertension in Africa in the allele contrast model, as well as the dominant, recessive and homozygous codominance model." (PMID 30763326, 2019). "The ACE Alu insertion polymorphism is a 287 base-pair insertion in intron 16 that has been associated with increased risk of hypertension and myocardial infarction." (PMID 30226856, 2018). "Secondary glomerulonephritis (GN) associated hypertension was treated with ACE (angiotenzine converting enzyme) inhibitors." (PMID 30053822, 2018). "Synthetic ACE inhibitors are produced as a treatment for hypertension, and although effective, the synthetic inhibitors cause side effects, including coughing, food taste alterations, rashes and reduced efficiency when used in the long term." (PMID 30235793, 2018). "Secondary GN-associated hypertension was treated with ACE (angiotensin converting enzyme) inhibitors." (PMID 30053822, 2018). "Frost, D also suggested that young T1DM patients exhibited a relationship between the prevalence of hypertension and frequency of the D allele mediated by the level of ACE." (PMID 29484134, 2018). "ACE is the most studied blood pressure candidate gene and has been associated with hypertension in European and African American populations." (PMID 30226856, 2018). "The most common variant of ACE gene, rs1799752, is associated with hypertension, heart failure and lifespan variation." (PMID 30159092, 2018). "As in hypertension, some studies implicate angiotensin converting enzyme (ACE) gene polymorphisms in the pathogenesis of T2DM, nephropathy and diabetic retinopathy." (PMID 29694640, 2018). "One study has reported a significantly higher risk of at-fault crash involvement with the use of ACE inhibitors in the elderly, medicines commonly used to treat hypertension." (PMID 28719606, 2017). "Persons with the D allele have higher plasma ACE levels and higher rates of hypertension, compared to carriers with the I allele." (PMID 28903744, 2017). "seeds, in an in vitro system by assessing their α-amylase, α-glucosidase (key enzymes linked to type-2 diabetes), and angiotensin-I converting enzyme (ACE) (key enzyme linked to hypertension) inhibitory activity." (PMID 28045446, 2017). "This study provides new information about the role of ACE1 within the MnPO in the hypertension associated with CIH and the potential use of ACE blockers that cross the blood‐brain‐barrier in treating hypertension of mild to moderate OSA patients." (PMID 28536140, 2017). "Previous studies found an association between the ACE insertion/deletion polymorphism and an increased risk of hypertension in OSA patients, although results are conflicting." (PMID 29093733, 2017). "Renin activates angiotensinogen into angiotensin I, and ACE can split angiotensin I into active angiotensin II, which can cause vasoconstriction and lead to high blood pressure." (PMID 29137154, 2017). "Positive associations with tinnitus were found with hypertension treatment with angiotensin-converting enzyme (ACE) inhibitors (p = 0.006), tiazidic diuretics (p < 0.0001), potassium-sparing diuretics (p = 0.016), and calcium channels blockers (p = 0.004)." (PMID 27761128, 2016). "Previous studies on ACE I/D polymorphism association with diseases mainly obesity and hypertension are too many worldwide." (PMID 27777603, 2016). "ACE inhibitors are known to be effective in the treatment of hypertension, however, they are also associated with a high incidence of coughing and other adverse effects." (PMID 26867195, 2016). "Thereafter, numerous studies focused on the association between ACE gene I/D polymorphism and hypertension." (PMID 28115791, 2016). "ACE I/D polymorphism association with hypertension has been extensively studied among different populations, and associations with obesity and insulin resistance have also been studied to a lesser extent." (PMID 27777603, 2016).